KPNB1 (karyopherin subunit beta 1)
Diseases named in the same sentence as KPNB1 in open-access papers (continued):
Sharing a sentence is not in itself a finding about the gene and the disease.
cervical cancer (7 papers, 2013 to 2023). A primary or metastatic malignant neoplasm involving the cervix. "KPNB1 regulates multiple stages of mitosis and inhibition of KPNB1 causes mitotic arrest in cervical cancer cells." (PMID 29520102, 2018). "Previous studies showed that knockdown of KPNB1 enhanced the sensitivity of cervical cancer cells to DDP." (PMID 35902727, 2022). "KPNB1 knockdown in cervical cancer cells inhibits cell growth by inducing prolonged mitotic arrest and apoptosis." (PMID 29520102, 2018). "KPNB1 expression has been found to be upregulated in various cancers including cervical cancer and correlates with a poor patient prognosis in gastric cancer." (PMID 28427184, 2017). "In our previous studies we have reported that KPNB1 is required for the survival and proliferation of cervical cancer cells and that inhibition of its expression and activity resulted in cell death via apoptosis." (PMID 28427184, 2017). "Using transwell migration assays, we showed that knocking down KPNB1 using siRNA reduced the ability of HeLa cervical cancer cells to migrate through the transwell membrane in the presence of PMA stimulation." (PMID 28427184, 2017). "A previous study demonstrated that KPNB1 was overexpressed in cervical cancer cells, and decreased expression of KPNB1 greatly reduced cell proliferation and triggered cell death procedures." (PMID 24369726, 2013). "As a result of this we wanted to investigate whether the changes is cervical cancer cell motility seen when KPNB1 was inhibited are potentially attributed to the inhibition of NFkB and AP-1 signaling." (PMID 28427184, 2017). "This work suggests that KPNB1 may play an important role in the migratory and invasive potential of cervical cancer cells." (PMID 28427184, 2017). "Here, we investigated the requirement of the nuclear import protein, KPNB1, for subcellular localisation of the NFkB p65/p50 dimer in cervical cancer cells using multiple techniques including; immunofluorescent analysis, nuclear/cytoplasmic protein separation and electromobility shift assays (EMSA)." (PMID 28427184, 2017). "Targeting KPNB1 as a means of transcription factor inhibition may be a favorable approach as KPNB1 is overexpressed in cervical cancer tissue in comparison to normal cervical tissue and we have previously shown that normal cells are less dependent on KPNB1 for proliferation and survival." (PMID 28427184, 2017). "Initially, their utility as biomarkers was suggested due to the detection of their protein content (KPNB1, CRM1, CAS, IPO5, and TNPO1) in the serum of patients with cervical cancer." (PMID 36992411, 2023). "For example, CRM1, KPNB1 and KPNA2 are overexpressed in cervical cancer cells." (PMID 31288861, 2019).
prostate carcinoma (7 papers, 2020 to 2025). A carcinoma that arises from epithelial cells of the prostate gland. "Prostate cancer cells with KPNB1 silencing exhibited low proliferation ability and tumor growth ability in vivo, which indicates the promoting effect of KPNB1 on the growth of cancer cells." (PMID 35902727, 2022). "Previous studies have reported that KPNB1 is dysregulated in a variety of cancers, such as prostate cancer, colorectal cancer, and lung adenocarcinoma." (PMID 35902727, 2022). "Currently, KPNB1 has been proved to play a promoting role in many types of cancer, such as non-small cell lung, prostate cancer, and colorectal cancer." (PMID 35902727, 2022). "Consistent with either of these non-mutually exclusive hypotheses, 893-PAL did not isolate importin-α proteins or nuclear pore proteins (Dataset EV2), and treatment with SH-BC-893 dramatically reduced the amount of KPNB1 present at the nuclear rim and in the nucleus of 22Rv1 prostate cancer cells." (PMID 40588551, 2025). "PPP2R1A and KPNB1 are particularly interesting candidate targets because PP2A activation and KPNB1 inhibition are validated therapeutic approaches in prostate cancer where both SH-BC-893 and FTY720 have demonstrated activity." (PMID 40588551, 2025). "These experiments demonstrate that SH-BC-893 reduces nuclear levels of prostate cancer drivers MYC and the AR by triggering PP2A-dependent proteasomal degradation and blocking KPNB1-mediated nuclear import in parallel, redundancy that could limit the development of drug resistance." (PMID 40588551, 2025).
ovarian carcinoma (6 papers, 2010 to 2024). A malignant neoplasm originating from the surface ovarian epithelium. "KPNB1 was identified as an oncogene in ovarian cancer through an invivo shRNA screen." (PMID 33488950, 2020). "The converse results were obtained when KPNB1 was overexpressed in ovarian cancer cells." (PMID 33488950, 2020). "High expression of KPNA2, but not KPNB1 is associated with poor prognosis in patients with ovarian cancer." (PMID 33488950, 2020). "Moreover, the ovarian cancer cells typically had higher transcript levels of importin 7 (Imp7) and importin B1 (ImpB1, also known as KPNB1), members of the karyopherin/importin-beta family of nuclear transport factors that have been shown in Drosophila to modulate MAPK/ERK nuclear localization." (PMID 20174585, 2010). "KPNB1 and KPNB2 expression did not correlate with clinical endpoints, such as stage, grade, or survival of ovarian cancer or chromosomal instability." (PMID 35013112, 2022).
lung carcinoma (5 papers, 2020 to 2026). "Since lung cancer is often treated with radiation therapy and our previous report demonstrated the involvement of KPNB1 in the malignancy of human LUAD cells, LUAD A549 cells were also used in the present study." (PMID 34069326, 2021). "Functional validation used primary CAFs from patients with NSCLC, including NRF2 perturbation, KPNB1 knockdown, T-cell co-culture assays, and an orthotopic murine lung cancer model treated with antiprogrammed cell death protein 1 (anti-PD-1)-based combinations." (PMID 42256528, 2026).
non-small cell lung carcinoma (5 papers, 2021 to 2025). A group of at least three distinct histological types of lung cancer, including non-small cell squamous cell carcinoma, adenocarcinoma, and large cell carcinoma. "TFRC and KPNB1 have been previously implicated in BC, while PUF60 has been associated with colon and non-small cell lung cancer." (PMID 35453681, 2022).
gastric cancer (4 papers, 2022 to 2025). A primary or metastatic malignant neoplasm involving the stomach. "We further analyzed the genes (such as MMP9, HMGA2, and KPNB1) in the gastric cancer cohort (TCGA‐STAD), and found that DR5 was positively correlated with them and higher than DR4." (PMID 37879960, 2023). "Previous studies have suggested that KPNB1 plays an important role in the malignant transformation of head and neck, lung and gastric cancer." (PMID 35864095, 2022). "Notably, DD1 combined with KPNB1 inhibitors effectively suppresses gastric cancer cell proliferation and tumor growth by enhancing both genomic and non-genomic activities of Nur77, suggesting KPNB1 as a promising therapeutic target in cancer treatment." (PMID 40370665, 2025).
head and neck squamous cell carcinoma (4 papers, 2020 to 2025). A squamous cell carcinoma that arises from any of the following anatomic sites: lip and oral cavity, nasal cavity, paranasal sinuses, pharynx, larynx, and salivary glands. "Our group recently reported that KPNB1 is involved in the malignancy of head-and-neck squamous cell carcinoma (HNSCC)." (PMID 34069326, 2021). "Furthermore, inhibiting KPNB1’s nuclear transport function suppressed PD-L1 expression level in irradiated human head and neck squamous cell carcinoma (HNSCC) cells." (PMID 33082305, 2020). "Here, we investigated the anticancer effects of KPNB1 blockage or in combination with ionizing radiation on human head and neck squamous cell carcinoma (HNSCC)." (PMID 32276424, 2020).
lung adenocarcinoma (4 papers, 2019 to 2022). A carcinoma that arises from the lung and is characterized by the presence of malignant glandular epithelial cells. "Down-regulation of KPNB1 induced by PLK1 inhibition caused apoptosis in lung adenocarcinoma." (PMID 36551208, 2022). "In addition, KPNB1 downregulation increased the cycle arrest of lung adenocarcinoma cells and induced apoptosis." (PMID 35902727, 2022). "Unsurprisingly, ΔNp63 expression was observed in only HNSCC cells, while the expression level of KPNB1 was noted in both HNSCC and lung adenocarcinoma cells." (PMID 32276424, 2020).
HIV-1 infection (3 papers, 2014 to 2018). The type species of lentivirus and the etiologic agent of acquired immunodeficiency syndrome (AIDS). "Despite the pleiotropic effects, KPNB1 depletion only moderately inhibited HIV-1 infection in HeLa cells, in a manner that was accentuated by aphidicolin treatment." (PMID 30084827, 2018).
colorectal cancer (2 papers, 2021 to 2022). A primary or metastatic malignant neoplasm that affects the colon or rectum. "Specifically, colorectal cancer cells with relatively low KPNB1 expression showed low migration and invasion capabilities." (PMID 35902727, 2022).
COVID-19 (2 papers, 2021). A disease caused by infection with severe acute respiratory syndrome coronavirus 2. "Decrease in KPNA3 (p = 0.0526) and increase in KPNB1 (p = 0.054) expressions were found with marginal significance in COVID-19 patients (I.I)." (PMID 34696514, 2021). "COVID-19 patients showed alterations in KPNA3, KPNA5, KPNA7, KPNB1, RHOA, and CDC42 expression compared with non-COVID-19 patients." (PMID 34696514, 2021).
leukemia (2 papers, 2022 to 2024). A malignant (clonal) hematologic disorder, involving hematopoietic stem cells and characterized by the presence of primitive or atypical myeloid or lymphoid cells in the bone marrow and the blood. "The canonical importin protein, importin β1, KPNB1, also ranked high on our CRISPR screen, but had a much lower enrichment in the LSC (3.6-fold) compared to bulk leukemia fractions." (PMID 35152270, 2022).
malignant peripheral nerve sheath tumor (2 papers, 2015 to 2020). Malignant peripheral nerve sheath tumor (MPNST) is a rare and often aggressive soft tissue sarcoma occurring in a wide range of anatomical sites. "In fact, there was a regulatory mechanism between hsa-miR-30d and KPNB1 in malignant peripheral nerve sheath tumor (MPNST)." (PMID 32175564, 2020). "Previously, we demonstrated that the EZH2/miR-30d/karyopherin (importin) beta 1 (KPNB1) signaling pathway is critical for malignant peripheral nerve sheath tumor (MPNST) cell survival in vitro and for tumorigenesis in vivo." (PMID 25890085, 2015).
melanoma (2 papers, 2022 to 2025). A malignant, usually aggressive tumor composed of atypical, neoplastic melanocytes. "Results of flow cytometry analysis showed that DDP treatment caused a significant increase in apoptotic rate, and melanoma cells with lower KPNB1 expression showed more apoptosis upon DDP exposure." (PMID 35902727, 2022). "Overall, the results suggested that KPNB1 expression was upregulated in melanoma and was associated with a poor prognosis." (PMID 35902727, 2022). "However, little is known about the function and underlying regulatory mechanism of KPNB1 in melanoma." (PMID 35902727, 2022). "We thus proposed that KPNB1 played a role in promoting melanoma development, and conducted gain-of- and loss-of-function experiments to test our hypothesis." (PMID 35902727, 2022). "The results showed that KPNB1 expression was clearly higher in melanomas tissues (n = 45) than that in benign skin nevus tissues (n = 18)." (PMID 35902727, 2022). "We further measured KPNB1 mRNA expression in melanoma cell lines and found that KPNB1 was highly expressed in melanoma cell lines (A2058, SK-MEL-1, SK-MEL-2, A875, and A375) compared with melanocytes." (PMID 35902727, 2022). "It was shown that subcutaneous injection of melanoma cells with KPNB1 silencing significantly reduced tumor volume and weight, whilst KPNB1-overexpressed cells injection increased the tumor volume and weight of mice." (PMID 35902727, 2022). "We found that KPNB1 knockdown significantly retarded the growth and metastasis of melanoma cells in vitro and in vivo, and increased their sensitivity towards the anti-tumor drug cisplatin." (PMID 35902727, 2022). "By analyzing the correlation between the expression of KPNB1 and the overall survival rate of melanoma patients, we found that melanoma patients with higher expression of KPNB1 had worse survival." (PMID 35902727, 2022). "In the present study, we demonstrated that KPNB1 was highly expressed in melanoma tissues and cells and survival was worse among melanoma patients with high KPNB1 expression." (PMID 35902727, 2022). "Following tail vein injection of melanoma cells with KPNB1 knockdown or overexpression in nude mice, lung metastasis was detected 7 weeks post-injection." (PMID 35902727, 2022). "Taken together, those findings suggested that KPNB1 promoted the growth and metastatic capacity of melanoma cells in vivo." (PMID 35902727, 2022). "We analyzed the microarray analysis data on KPNB1 mRNA expression in 45 primary melanomas and 18 benign skin nevus tissues in the previous study." (PMID 35902727, 2022). "Similar to previous studies, in vivo and in vitro experiments demonstrate that KPNB1 overexpression is beneficial to the survival and metastasis of melanoma cells." (PMID 35902727, 2022). "Overall, those results indicated that KPNB1 contributed to the growth, migration, and invasion capabilities of melanoma cells." (PMID 35902727, 2022). "Additionally, KPNB1 KD was able to halve the amount of endogenous ERK5 in the nucleus in A375 melanoma cells with respect to siNT‐treated ones." (PMID 38965815, 2025). "KPNB1 overexpression contributed to melanoma cell growth and metastasis in vivo and in vitro." (PMID 35902727, 2022). "Notably, in melanoma cells, KPNB1 overexpression significantly decreased Ras-GTPase-activating protein SH3 domain-binding protein 1 (G3BP1) protein level, which was also overexpressed in melanoma samples and enhanced malignant behaviors of melanoma cells." (PMID 35902727, 2022). "Furthermore, the database analyzed that the KPNB1 mRNA level was higher in melanoma samples than that in skin nevus tissues." (PMID 35902727, 2022). "In summary, our results also suggest that KPNB1 may be a potential molecular target for melanoma therapy." (PMID 35902727, 2022). "We further explored the mechanism by which KPNB1 is involved in melanoma progression." (PMID 35902727, 2022).
melanoma (continued). "In summary, this study mainly reports that KPNB1 may promote melanoma progression by stabilizing the G3BP1 protein." (PMID 35902727, 2022). "Functional analysis indicated that G3BP1 knockdown reversed the effect of KPNB1 on the malignant phenotype of cells, indicating that the regulation of KPNB1 on the development of melanoma may be achieved through G3BP1." (PMID 35902727, 2022). "Moreover, results of the GSE183115 database also confirmed that KPNB1 mRNA expression was significantly increased in melanomas tissues (n = 4) compared with nevus tissues (n = 4)." (PMID 35902727, 2022). "Conversely, KPNB1 overexpression protected melanoma cells from DDP-mediated apoptosis." (PMID 35902727, 2022). "Our observations suggest that the development of drugs targeting KPNB1 as well as genetic tools may provide direction for the treatment of melanoma." (PMID 35902727, 2022). "Therefore, the results suggest that KPNB1 may promote melanoma progression by stabilizing the G3BP1 protein." (PMID 35902727, 2022). "Altogether, we mainly investigated the functions of KPNB1 and G3BP1 in melanoma and their regulatory relationship." (PMID 35902727, 2022). "Therefore, G3BP1 might mediate the regulation of KPNB1 on melanoma progression." (PMID 35902727, 2022). "Given that KPNB1 could upregulate G3BP1 expression, we next investigate the role of G3BP1 in KPNB1–mediated melanoma progression." (PMID 35902727, 2022). "However, in addition to G3BP1, KPNB1 can also play a role in cancer by regulating the nuclear transport of substrates, such as E2F transcription factor 1 (E2F1) and p65, which play a promoting role in melanoma." (PMID 35902727, 2022). "Similarly, the present study suggested that melanoma cells with lower KPNB1 expression showed more apoptosis upon DDP exposure, which indicates that overexpression of KPNB1 in melanoma may contribute to the generation of DDP resistance." (PMID 35902727, 2022). "Interestingly, we found that KPNB1 only affected the protein expression of G3BP1 but not the mRNA level, and KPNB1 downregulation increased the ubiquitination of G3BP1 in melanoma cells, which is similar to previous." (PMID 35902727, 2022).
proteinopathies (2 papers, 2022 to 2024). "Based on our findings in cellular models of TDP-43 proteinopathy, we proposed that 1) there are additional KPNB1 interaction domains present in TDP-43 and 2) additional factors missing in in vitro fibrillization studies but present in cellular TDP-43 aggregates can facilitate this process." (PMID 36482422, 2022). "The same question also applies to KPNB1 which accumulates in TDP-43-positive inclusions in ALS/FTD, while it can efficiently reduce TDP-43 pathology in models of TDP-43 proteinopathy." (PMID 38254150, 2024). "Our finding that both Nup62 and KPNB1 are recruited to all pTDP-43 inclusions in ALS/FTD patients, strongly supports the relevance of our data from disease models for human TDP-43 proteinopathies." (PMID 36482422, 2022). "KPNB1 then either disengages or prevents intermolecular interactions in FG-Nups and TDP-43 PrLD fibrils, leading to soluble TDP-43 in complex with KPNB1 being imported into the nucleus, reversing all major hallmarks of TDP-43 proteinopathy." (PMID 36482422, 2022). "KPNB1 and other β-type importins mitigate aggregation, mislocalization and neurotoxicity of TDP-43 variants lacking its classical NLS across different models of TDP-43 proteinopathy." (PMID 38254150, 2024).
adrenal cortical carcinoma (1 paper, 2020). "Based on our analysis, we speculated that KPNB1 played an important role in the metastasis of adrenal cortical carcinoma." (PMID 32175564, 2020).
Alzheimer disease (1 paper, 2021). A progressive, neurodegenerative disease characterized by loss of function and death of nerve cells in several areas of the brain leading to loss of cognitive function such as memory and language. "KPNB1 and KPNB2 were found in cytoplasmic granules in hippocampal neurons, while KPNB2 accumulation was also detected in tangle-bearing cells of Alzheimer’s disease cases." (PMID 34019093, 2021). "Expression of KPNB1 and XPO5/exportin-5 were both found to be upregulated in Alzheimer’s disease cases and both proteins co-localized with hyperphosphorylated tau." (PMID 34019093, 2021).
Atrophy (1 paper, 2025). Any weakening or degeneration, especially through lack of use. "Other studies have shown a clear role for KPNA/KPNB1-mediated nuclear transport in disorders like HSP or spinocerebellar ataxia, a disease characterized by atrophy of the cerebellum and progressive loss of coordination." (PMID 40565582, 2025).
depression (1 paper, 2025). "In summary, through bioinformatics and machine learning approaches, we have identified histone acetylation-related biomarkers ALOX5, JDP2, and KPNB1 associated with depression." (PMID 40370665, 2025).
endometriosis (1 paper, 2022). The growth of functional endometrial tissue in anatomic sites outside the uterine body. "The upregulated expression of MAP3K5 and KPNB1 suggests that they may be involved in the apoptosis of GCs, which is consistent with the study that GCs from patients with endometriosis show increased levels of apoptosis." (PMID 35295989, 2022).